MAVS (mitochondrial antiviral signaling protein)
Diseases named in the same sentence as MAVS in open-access papers (continued):
Sharing a sentence is not in itself a finding about the gene and the disease.
infection (continued). "The cells were co-transfected with Flag-MAVS and hemagglutinin (HA)-Ub plasmids, followed by aMPV/C infection and an immunoprecipitation assay at 48 h." (PMID 34696420, 2021). "In conclusion, our study demonstrated for the first time that aMPV/C infection mediated MAVS degradation in Vero cells." (PMID 34696420, 2021). "In infections with other viruses, MAVS cleavage was a result of apoptosis-activated degradation, autophagic degradation or ubiquitin-proteasome pathways." (PMID 33807534, 2021). "Collectively, these results indicate that aMPV/C infection promotes the formation of polyubiquitin chains and final degradation of MAVS." (PMID 34696420, 2021). "Because MAVS is a critical component of the type-I IFN antiviral signaling cascade, many viruses have evolved strategies for evading host antiviral immunity by targeting MAVS to achieve successful infection." (PMID 34578357, 2021). "Tom70 also has a broader role in RNA viral infection recognition through interaction with the mitochondrially localized protein MAVS which, together with other cytosolic proteins, form the MAVS signal complex following infection." (PMID 34064787, 2021). "Previous studies showed that infection of HEK293T cells with SeV enhanced the interaction of TRAF3 with both its upstream regulator MAVS and downstream effector TBK1." (PMID 33411856, 2021). "Here, we confirmed that aMPV/C infection induced a reduction in MAVS expression in Vero cells in a dose-dependent manner, and active aMPV/C replication was required for MAVS decrease." (PMID 34696420, 2021). "KSHV targets RIG-I/MAVS signaling not only during initial infection but also during viral reactivation." (PMID 34440891, 2021). "MAVS and MDA5 knockout mice lose type I interferon production and suffer early mortality in response to infection with the Coxsackie B virus (CVB), which has been associated with myocarditis." (PMID 34503262, 2021). "In this study, we demonstrated that aMPV/C infection induced MAVS degradation via the proteasome pathway in the cultured cells, and this degradation was largely blocked in the presence of MG132." (PMID 34696420, 2021). "pUL37x1, or viral mitochondria-localized inhibitor of apoptosis (vMIA), is expressed at immediate-early times of infection, at which point it acts to suppress MAVS signaling." (PMID 34440891, 2021). "Silencing MyD88 which is activated by TLR7 or silencing MAVS which is activated by MDA5 in microglia exposed to exosomes secreted by microglia during TMEV infection reduced the expression of type I interferons." (PMID 34485270, 2021). "Since it was initially found that the decrease in MAVS expression occurred at 48 h after infection, we analyzed which regulation of transcription or translation played a major role in the decrease in MAVS." (PMID 34696420, 2021). "This differs from MAVS ubiquitination mediated by infection with NDV, which is another member of the Paramyxoviridae family." (PMID 34696420, 2021). "We further studied the interaction of endogenous MAVS with IAV NS1 during infection by a replication-competent reporter IAV expressing FLAG-tagged NS1." (PMID 34696339, 2021). "Expression of MAVS gradually decreased over the 120 h after aMPV/C infection, whereas the amount of MAVS mildly increased in mock-infected Vero cells." (PMID 34696420, 2021). "In summary, our data suggest that RNF90, the expression of which is induced by the infection of RNA viruses, negatively regulates MAVS-mediated innate immune responses against RNA viruses." (PMID 34512666, 2021). "Independent of its role in apoptosis, vMIA also counters RIG-I/MAVS by degrading RIG-I following infection of primary human foreskin fibroblasts." (PMID 34440891, 2021). "Although the effect of IFN on virus replication after MAVS degradation cannot be studied in aMPV/C-infected Vero cells, the study of aMPV/C infection degrading MAVS through ubiquitination enriches the interaction between virus and host cells." (PMID 34696420, 2021).
infection (continued). "In summary, we have identified a deubiquitinase USP18 as a host factor modulating MAVS aggregation during the infection of RNA viruses." (PMID 34016972, 2021). "We observed a variation in the protein level of MAVS and NF-κB p65 during the period of infection; MAVS was induced at day 1 of the acute infection phase, and then reduced to a modest protein level." (PMID 32121148, 2020). "In our setting, H7-2 WT infection at an MOI of 1 strikingly reduced MAVS protein level as early as at 6 hpi, leading to an inhibition of type I IFN production at 12 and 24 hpi." (PMID 32511263, 2020). "RLRs recognize invasive viral RNA produced during infection and mediate the induction of Type I Interferons via the mitochondrial antiviral signaling (MAVS) molecule." (PMID 32983015, 2020). "West Nile virus (WNV) infection of mice deficent of RLR-signaling adaptor MAVS results in a defective adaptive immune response." (PMID 33104760, 2020). "(H) Percentage infection of control, cGAS-/-or MAVS-/- THP-1 knock out cells infected with HIV-GFP at indicated doses of RT (SG-PERT)." (PMID 33300875, 2020). "We found that fish MAVS acts as a crucial signaling molecule in the infection of SCRV, which mediated both the NF-κB and IRF3 activation and lead to type I IFNs and inflammatory cytokine production." (PMID 32678830, 2020). "We elaborate that fish MAVS contributes to IFN antiviral immunity following the infection of Siniperca chuatsi rhabdovirus (SCRV), a typical fish RNA rhabdovirus." (PMID 32678830, 2020). "Here, we showed that a lncRNA MARL, which was upregulated upon SCRV infection, can modulate MAVS expression through competitively sponging miR-122 in lower vertebrate, miiuy croaker." (PMID 32678830, 2020). "When we explored its effect on cell viability using luminescent cell viability assay, knockdown of MAVS resulted in a decline in cell viability upon SCRV infection." (PMID 32678830, 2020). "Compared with uninfected A549 cells, infection with FM-MA induced MAVS-dependent expression of IFN-β and IFN-λ1 genes as early as 3 h postinfection, which increased to 50-fold and 150-fold, respectively, by 17 h postinfection." (PMID 32321802, 2020). "MAVS-deficient mice also exhibit increased viral titers and mRNA levels of the RSV F and N proteins on day four post-infection." (PMID 32290326, 2020). "In particular, after infection MAVS-/- mice had significant increases specifically in the IgM- cells, both CD19+ plasmablasts and CD19- plasma cells; these cells are most likely IgG-secreting." (PMID 31242236, 2019). "Infection of MAVS–/– mice revealed enhanced WNV replication and viral-induced lethality due to increased inflammation in the brain." (PMID 31652496, 2019). "Infection with Semliki Forest virus induces apoptotic cell death through caspase-8 activation via the MAVS pathway highlighting that there can be a direct death inducing signal triggered by MAVS." (PMID 31131275, 2019). "After WNV-MAD infection Ab responses and viral titers were significantly higher in MAVS-/- mice than in WT mice." (PMID 31242236, 2019). "Nonetheless, WNV-MAD replicates well in the absence of MAVS, with almost 100-fold more virus detected in MAVS-/- mice in the spleen 7 days after infection compared to WT mice." (PMID 31242236, 2019). "Previously, we reported that 6 days after WNV-TX infection MAVS-/- mice had about 200-fold higher levels of serum WNV-specific IgG compared to WT mice." (PMID 31242236, 2019). "While approximately 25% of WT and 100% of MAVS-/- naïve mice succumbed to WNV-TX infection by day 9, all of the WNV-MAD infected mice survived a lethal challenge." (PMID 31242236, 2019). "The expression of RIG-I, MAVS, and NF-κB p65 was reported to increase significantly after infection with influenza virus, suggesting that the RLRs signaling pathway and its downstream signaling factors are activated in immune cells." (PMID 31757053, 2019).
infection (continued). "The results revealed that MAVS protein was cleaved in EV71 infected RD cells after nine hours of infection." (PMID 31817126, 2019). "In contrast, NLK bound strongly to MAVS after exposure to the virus in the later phase of infection." (PMID 31324787, 2019). "This was indeed the case; we detected an over 2-fold increase in TFH cells in MAVS-/- mice compared to WT mice 7 days after WNV-MAD infection." (PMID 31242236, 2019). "As these data would predict, we found significantly elevated B220lo CD138+ plasma cells in MAVS-/- mice compared to WT mice following WNV-MAD infection as early as day 7 and up to day 10 p.i.." (PMID 31242236, 2019). "Introducing the dsRNA mimic poly(I:C) into MEFs by electroporation (0.6–1 pg per cell) recapitulated the changes in MAVS distribution and mitochondrial morphology observed upon infection with the WNV replicon." (PMID 30715798, 2019). "Strikingly, WNV-TX-infected MAVS-/- mice had elevated levels of virus-specific Ab responses; six days after infection IgG Ab levels were about 200 times higher in infected MAVS-/- mice than wildtype (WT) mice." (PMID 31242236, 2019). "MAVS-deficient (MAVS-/-) mice infected with a pathogenic strain of WNV, WNV-Texas (TX), uniformly died from infection within 8–9 days post infection (p.i.)." (PMID 31242236, 2019). "Control MAVS−/− mice administered rat IgG remained protected from rJHMVPS−; conversely, MAVS−/− mice administered IFNAR-blocking antibody displayed increased weight loss and succumbed to infection." (PMID 29717007, 2018). "We also determined the contribution of each RLR sensor and MAVS to KSHV de novo infection of iSLK cells." (PMID 30451863, 2018). "For example, infection of mice deficient in the adaptor downstream of RIG-I and MDA5, mitochondrial antiviral signaling (MAVS), revealed that RIG-I-like receptors and MAVS are essential for innate protective immunity against WNV." (PMID 29408905, 2018). "Next, to determine if IFN-I signaling during infection was responsible for protecting mice or if basal levels of ISGs were playing a significant role, we treated MAVS−/− mice with an IFNAR-blocking antibody." (PMID 29717007, 2018). "To gain additional mechanistic insights into the sequential events leading to MAVS degradation, we sought to identify possible post-translational modifications (PTMs) on MAVS during infection." (PMID 30460894, 2018). "A diminished IFN-λ response to EW infection is consistent with MAVS inhibition and disruption of the IFN induction pathway." (PMID 30460894, 2018). "The abundance of intracellular ZIKV RNA was modestly higher in RIG-/- and MDA5-/- than wild type (WT) cells at 36 and 72 h after infection, while it was dramatically increased by ∼20–40 times in MAVS-/- compared to WT cells." (PMID 29988497, 2018). "WNV replication in the spleens of WT mice typically peaks about day 4 p.i., and then decreases and is cleared within 6 to 8 p.i.; this course of infection is evident even in innate immune defective MAVS-/- mice." (PMID 29408905, 2018). "HCMV∆US7-16 infection enhanced mitochondrial MAVS for activation, which was similar results observed in uninfected cells (lane 3)." (PMID 29317664, 2018). "MAVS-mediated antiviral signaling has been well recognized as a major mechanism for host cell defense against infection by viruses, particularly H5N137,38." (PMID 29327729, 2018). "At different times post-infection, protein lysates were harvested and analyzed for the presence of the MAVS protein and MRV infection." (PMID 28883463, 2017). "At 12 hpi, for both virion and ISVP infected cells, a slight increase in the amount of MAVS was observed particularly during ISVP infection." (PMID 28883463, 2017). "IBV can efficiently cleave MAVS in the early stages of infection, leading to the blockage of IFN expression." (PMID 29132350, 2017). "We found that TRAF2, 3, and 6 but not TRAF5 showed induced interaction with MAVS, confirming that multiple TRAFs were recruited to MAVS upon infection." (PMID 29125880, 2017).
infection (continued). "Upon infection, the TRAFs-TBK1/IKKε complex was recruited to MAVS, likely bringing TBK1/IKKε close enough to cause the trans-autophosphorylation." (PMID 29125880, 2017). "This discovery uncouples the role of the TNF pathway in dictating the individual cell fate during infection and identifies the interaction of DVGs with the MAVS-mediated antiviral pathway as a critical factor in defining cell survival upon infection." (PMID 28986577, 2017). "Both CVB3 proteinase 2Apro and 3Cpro trigger MAVS cleavage at different sites during infection, and the cleavage of MAVS by EV71 is accomplished via its 2Apro activity." (PMID 28096803, 2016). "Significant down-regulation of MAVS mRNA and protein levels at 12, 24, and 36 h post- infection was also observed." (PMID 27705941, 2016). "As such, mice deficient in RIG-I or MAVS showed delayed viral clearance and recovery from primary IAV infection, and decreased protection against subsequent infection from a heterologous IAV strain." (PMID 27438481, 2016). "In one study, expression of poliovirus, CVB3, or EV71 2A proteinase alone resulted in MDA5 and MAVS cleavage similar to what is observed during infection." (PMID 27999393, 2016). "In conclusion, we demonstrated an additional mechanism involved in DENV-ADE infection, in which cross-reactive antibodies mediated infection by inducing autophagy related proteins to suppress the innate immunity mediated by MAVS directed ISGs activation." (PMID 26923481, 2016). "Next, we investigated if RIG-I-/- BMDC respond to signaling via the MDA5 –MAVS pathway by performing infections with Encephalomyocarditis virus (EMCV)." (PMID 27438481, 2016). "Taking advantage of this cell system, we next determined the impact of MAVS cleavage and MAVS subcellular localization on activation of the IFN response by HCV in an infection-based system." (PMID 26588843, 2015). "IKKβ activation during MHV68 infection is at least partially mediated through activation of the MAVS adaptor protein." (PMID 26584434, 2015). "While core protein stimulates the TLR2 pathway that assists the virus to evade the innate immune system, NS3/4A disrupts TLR3 and RIG-1 signaling pathways by cleaving TRIF and MAVS, which leads to persistence of infection." (PMID 25664450, 2015). "Together, this data suggests that immune activation induced by infection in the presence of antibody utilizes canonical transduction pathways known to be downstream of MAVS and STING." (PMID 26506431, 2015). "Mitochondrial MAVS signaling occurs later in infection, triggering IFN expression and induction of ISGs, and sustaining the immune response." (PMID 26001115, 2015). "Having established the comparable activation of type I and III IFN response by mito- and pexMAVS, we wanted to clarify the relative impact of either MAVS species on the IFN response during infection with HCV." (PMID 26588843, 2015). "In order to confirm the role of NSP1 on MAVS aggregate formation, HEK293 cells were transfected with pcD-NSP1 and FLAG-MAVS protein followed by infection with A5-16 (NSP1 mutant) strain, in presence of either MG132 or DMSO." (PMID 24643253, 2014). "There was no significant change of MAVS mRNA and thus the degradation of MAVS after infection was confirmed as a post-transcriptional phenomenon." (PMID 24643253, 2014). "Except for A5-16 where a truncated NSP1 is synthesized, infection with all other strains abrogated MAVS by almost 50% compared to the mock infected control, whereas IRF3 degradation was observed only in A5-13, EW and RRV strains." (PMID 24643253, 2014). "Infection by Sendai virus induced the redistribution of MAVS protein and the formation of densely packed, speckled MAVS puncta on the surface of mitochondria, along with the nuclear translocation of NF-κB subunit p65 and induction of interferon-β (IFNβ)." (PMID 24569476, 2014).
infection (continued). "Accordingly, as anticipated, siRNA mediated knock-down MAVS extensively inhibited type I IFN production of A549 cells during infection with L. monocytogenes." (PMID 23653683, 2013). "This correlated with virus control as infected wild- type, MAVS and IRF3/7 deficient epithelia had similar virus titers over the course of infection." (PMID 24278020, 2013). "To explore if CDCA facilitates infection of particles released after transfection of these genomes, we co-cultured Lunet cells transfected with these genomes with naïve Lunet MAVS-GFP cells." (PMID 22558311, 2012). "In summary, here we have demonstrated that phosphorylation modification is involved in the control of MAVS activity in innate immune response, which thereby provides positive regulation of the innate antiviral response against infection by RNA viruses." (PMID 22844514, 2012). "Although the role of the MAVS pathway during S. flexneri infection remains to be fully elucidated, these findings suggest that early during infection the MAVS pathway plays a small role in the inhibition of S. flexneri replication in vivo." (PMID 22912573, 2012). "HEp-2 cells were mock-infected or infected at an MOI of 1 with either rA2or rA2 ΔNS1 orrA2 ΔNS2 and at 24 h post-infection (p.i.), total cell lysates were immunoprecipitated with anti-MAVS antibody and analyzed by western blotting with anti-NS1 antiserum." (PMID 22383950, 2012). "During early infection, γHV68 hijacks MAVS and IKKβ to induce the site-specific phosphorylation of RelA, a crucial subunit of the transcriptionally active NFκB dimer, which primes RelA for the proteasome-mediated degradation." (PMID 22110409, 2011). "cDCs derived from MAVS-/- mice responded to S. pyogenes-derived RNA-containing extracts or to infection with live S. pyogenes by normal IFN-β induction." (PMID 21625574, 2011). "When we tested cells deficient in the mitochondrial helicase adapter MAVS (also known as IPS-1, VISA or CARDIF) we also found a significant reduction in Noxa-promoter induction upon infection with MVA or MVAΔF1L." (PMID 21698224, 2011). "Presumably, the activation kinetics of the MAVS-IKKβ pathway depends on the multiplicity of infection per cell, and higher doses of infectious γHV68 favor earlier and more robust activation of IKKβ and termination of NFκB." (PMID 22110409, 2011). "We found that infection of cells with CVB3 led to the cleavage of the adaptor molecules MAVS and TRIF." (PMID 21436888, 2011). "To quantitatively determine the effect of MAVS on γHV68 lytic infection, we examined γHV68 lytic replication in MAVS+/+ and MAVS−/− MEFs by plaque assays." (PMID 20686657, 2010). "Our results show that HCV infection can stimulate the IFN induction pathway up to 12 hrs post-infection, whereas detection of MAVS cleavage begins at 18 hrs post-infection and is maximal at 24 hrs." (PMID 20485506, 2010). "In our experimental conditions, MAVS cleavage was clearly detected in both cell types at 48 hrs after infection with JFH1." (PMID 20485506, 2010). "At a low MOI (0.01), analyses by PCR and real-time PCR revealed comparable levels of viral genomes in MAVS+/+ and MAVS−/− MEFs early after de novo infection, suggesting comparable viral entry into MAVS+/+ and MAVS−/− MEFs." (PMID 20686657, 2010). "Surprisingly, γHV68 displayed delayed replication kinetics in MAVS−/− MEFs compared to MAVS+/+ MEFs at multiplicities of infection (MOI) of 0.01 and 0.1." (PMID 20686657, 2010). "The antiviral effects of MAVS have been observed against the infection of a number of RNA and DNA pathogens." (PMID 20686657, 2010). "NS3/4A expression was detected around 18 hrs post-infection, and MAVS cleavage after 24 hrs post-infection." (PMID 20485506, 2010). "Furthermore, whereas infection of MAVS WT cells with SeV or VSV-GFP induced type I IFNs, this response was significantly suppressed in cells expressing the phosphorylation-deficient MAVS 2SA mutant." (PMID 40837220, 2025).